EPO (erythropoietin)
Diseases named in the same sentence as EPO in open-access papers (continued):
Sharing a sentence is not in itself a finding about the gene and the disease.
cerebral palsy (18 papers, 2013 to 2025). A group of disorders affecting the development of movement and posture, often accompanied by disturbances of sensation, perception, cognition, and behavior. "Cerebral palsy was reported in 13.4% of the erythropoietin group and 22.8% of the control group (risk ratio 0.47 (95% CI: 0.28–0.80))." (PMID 34175900, 2021). "Our analysis shows that erythropoietin significantly reduced the risk of death or neuro-disability and cerebral palsy in the three studies with outcome reported at 18 months of age." (PMID 34175900, 2021). "The EPO-treated group had a lower risk of cerebral palsy and showed less neurological abnormalities using MRI." (PMID 32098276, 2020). "Among neonates treated for HIE, the use of erythropoietin (0.36; 0.18-0.74, 2 trials) and whole body hypothermia (0.61; 0.45-0.83; 7 trials) were associated with lower rates of cerebral palsy." (PMID 31708771, 2019). "This 1-year open-label extension study aimed to identify the persistent synergistic effects of allogeneic umbilical cord blood (UCB) cells and erythropoietin (EPO) in children with cerebral palsy (CP) for up to 2 years." (PMID 38087394, 2023). "With respect to cerebral palsy, 5 studies were included into this meta-analysis (EPO group/control group = 408/406)." (PMID 36699298, 2022). "For example, the meta-analysis at 2019 showed EPO was helpful to decrease incidence of cerebral palsy." (PMID 36699298, 2022). "Only erythropoietin has been studied in primates with follow-up included allowing for anticipated effect sizes for death or cerebral palsy as a combined outcome measure to be determined." (PMID 34820702, 2022). "A meta-analysis at 2019 also showed EPO administration in neonates with perinatal HIE reduces the risk of brain injury, cerebral palsy and cognitive impairment." (PMID 36699298, 2022). "Our previous clinical studies demonstrated the synergistic therapeutic effect induced by co-administering recombinant human erythropoietin (rhEPO) in human umbilical cord blood (hUCB) therapy for children with cerebral palsy." (PMID 34769434, 2021). "Concomitant administration of allogeneic umbilical cord blood (UCB) infusion and erythropoietin (EPO) showed therapeutic efficacy in children with cerebral palsy (CP)." (PMID 33246489, 2020). "The major findings of the study were that, while HT alone did not reduce the risk of death or moderate-severe cerebral palsy after umbilical cord occlusion, HT combined with four doses of EPO significantly reduced this risk to 0%." (PMID 32098276, 2020). "Particularly, since the first published double-blind randomized placebo-controlled trial in a paradigm using allogeneic cord blood and erythropoietin to treat cerebral palsy under imunosuppression showed beneficial therapeutic effects in infantile cerebral palsy." (PMID 24695413, 2014). "Other disorders, such as cerebral palsy, start with a discrete lesion early in development and express varied developmental phenotypes, with neuroplasticity occurring in response to use-driven rewiring of circuits or the introduction of neuroprotective agents (e.g., erythropoietin, caffeine)." (PMID 30891437, 2019). "Despite some studies evaluating the role of innovative neuroprotective therapy (i.e., stem cells, erythropoietin (EPO), vitamin E, and melatonin), the early diagnosis of IVH/PVL is still the gold-standard to reduce a long-term neurological consequence, such as cerebral palsy (CP)." (PMID 36829868, 2023). "As for neurodevelopmental impairment (including cerebral palsy and epilepsy), no significant beneficial effect of EPO was found in our study either." (PMID 36699298, 2022). "• Clinical study showed lower incidence of cerebral palsy in infants. • An open-label pilot study showed that combination of MgSO4, erythropoietin and TH was found to be safe." (PMID 34504417, 2021). "Treatment with EPO plus hypothermia led to less cerebral palsy in a non-human primate model of perinatal asphyxia, leading to clinical trials." (PMID 32098276, 2020).
melanoma (18 papers, 2008 to 2025). A malignant, usually aggressive tumor composed of atypical, neoplastic melanocytes. "Overall, SPO displayed broader and stronger bioactivity than EPO across assays, whereas EPO showed selective advantages against Candida albicans and, in our viability panel, a notable potency in A375P melanoma at high dose." (PMID 41598205, 2025). "Accordingly, the pronounced effect of EPO in A375P melanoma cells points to terpenoid-centric mechanisms." (PMID 41598205, 2025). "EPO knockdown in melanoma cells led to a decrease in EPO phosphorylation in response to EPO stimulation, a decrease in cell proliferation, and an increased response to the inhibitory effect of hypoxia and cisplatin in vitro." (PMID 37894821, 2023). "The expression of erythropoietin receptor mRNA was shown in 90.1% of 65 melanoma cell lines, and an increase in the number of copies of EPO and EPO loci was observed in 30 and 24.6% of 130 primary melanomas, respectively." (PMID 37894821, 2023). "EPO activates the PI3K/AKT pathway in human melanoma cells and both the antiapoptotic and proliferative effect of EPO acting through the AKT and ERK pathways in neuroblastoma cancer cells were observed." (PMID 34299300, 2021). "Our results indicate that EPO exerts a powerful stimulatory effect on cell proliferation and de novo protein synthesis in melanoma cells through activation of the initiation factor eIF4E." (PMID 28415825, 2017). "Using eIF4E siRNAs, we observed that downregulation of eIF4E expression in B16 melanoma cells can profoundly reverse the EPO-induced increase in melanoma cell proliferation, suggesting that EPO-mediated melanoma tumor cell growth is eIF4E-dependent." (PMID 28415825, 2017). "In the present study we sought to explore the effect of EPO administration on the development of established murine melanoma." (PMID 28415825, 2017). "In our studies, the impact of EPO treatment on melanoma cell growth was further confirmed by in vitro proliferation experiments." (PMID 28415825, 2017). "To test the effect of EPO on melanoma tumor growth in vivo, we used a well characterized B16 melanoma tumor model." (PMID 28415825, 2017). "Instead, our result indicate that treatment of B16 melanoma cells with EPO results in activation of several cell signaling pathways that eventually lead to phosphorylation of 4E-BP1." (PMID 28415825, 2017). "Employing an in vivo model of B16 murine melanoma, we observed that administration of EPO to tumor bearing C57BL/6 mice resulted in pronounced acceleration of melanoma growth." (PMID 28415825, 2017). "To define a functional role for the EPO-R on melanoma cells, we performed cell culture experiments using recombinant EPO." (PMID 24489649, 2014). "The structure of LacdiNAc is frequently found in glycoproteins of tumorous cells, including recombinant EPO from ovarian carcinoma cells, ribonuclease 1 from pancreatic adenocarcinoma cells, and tissue plasminogen activator from Bowes melanoma cells." (PMID 25003232, 2014). "For this purpose, melanoma cell lines were exposed to various cytokines (EPO, EGF, TGF-ß1, Heregulin-α, IGF-1, HGF, SCF, NGF) and then were subjected to qPCR analysis and flow cytometry." (PMID 24489649, 2014). "Erythropoietin and Epo-R have been shown to be expressed in a number of cancers and involved in breast, endometrial, melanoma, prostate and Barrett's oesophageal carcinogenesis." (PMID 18283323, 2008). "Erythropoietin and its receptor (Epo-R) are expressed in a number of cancers and are involved in breast, endometrial, melanoma and prostate tumorigenesis." (PMID 18283323, 2008). "In a mouse melanoma tumor model, it has been shown that increased angiogenesis in Beclin1-deficient mice primarily related to an elevation of erythropoietin rather than VEGF." (PMID 40735300, 2025).
melanoma (continued). "Additionally, loss of VHL was connected to increased skin vascularization, which is known to contribute to growth and angiogenesis, potentially through iNOS and EPO signaling, in many cancers including melanoma." (PMID 28806730, 2017). "Since Erk, a kinase that plays a major role in mediating oncogenic signals, is hyperactivated in 90% of human melanomas, the additional stimulatory effects by EPO may critically affect survival and proliferation of melanoma cells." (PMID 28415825, 2017). "Indeed, EPO-induced angiogenesis in Matrigel plug assays, and neutralization of EPO secreted by melanoma cells resulted in decreased angiogenesis, which supports the role of EPO/EPOR in melanoma progression via angiogenesis stimulation." (PMID 25426117, 2014). "In addition, we were able to show that the same melanoma cells that were recognized by the anti-EPO-R antibody also bind biotinylated recombinant EPO on their surface." (PMID 24489649, 2014). "Expression of the EPO-R on melanoma cells could also be confirmed by using directly labeled (biotinylated) rh EPO." (PMID 24489649, 2014). "SPO may be considered for further evaluation as a multi-component source of anti-inflammatory and antimicrobial activity, whereas EPO may warrant follow-up studies focusing on antifungal activity and melanoma cell growth inhibition, pending additional validation." (PMID 41598205, 2025). "However, in erythroleukemic cells, EPO downregulates KIT expression and malignant transformation of melanocytes leads to a loss of KIT expression and upregulation of EPOR expression in melanoma cells." (PMID 35887076, 2022). "Importantly, our studies demonstrate, for what we believe to be the first time that stimulation of melanoma cells with therapeutic concentrations of EPO induced an increase in phosphorylation, and therefore activation of the translational regulatory protein eIF4E." (PMID 28415825, 2017). "EPO induced angiogenesis in Matrigel plug assays, whereas neutralization of EPO secreted by melanoma cells resulted in decreased angiogenesis, which supports the role of EPO/EPOR in melanoma progression via stimulation of angiogenesis." (PMID 28703764, 2017). "Despite the absence of melanoma growth stimulation in vivo, EPO increased vascular size in the xenografts." (PMID 25426117, 2014). "Importantly, EPO/EPOR levels correlated well with angiogenesis and progression of patients with hepatocellular, squamous cell of the tongue and non-small cell lung carcinomas, neuroblastoma, melanoma, and gastric adenocarcinoma." (PMID 28703764, 2017). "However, in the current study EPO was neither found to induce proliferation nor to enhance viability in melanoma cells." (PMID 24489649, 2014). "In this regard, EPO-mimetic peptide 9 (EMP-9) decreases the angiogenesis of the stomach, choriocarcinoma SCH, and melanoma P39, but does not affect the vessels in the host." (PMID 28703764, 2017). "However, we were unable to detect any significant effects of EPO, SCF, Heregulin-α or TGF-β1 on growth of melanoma cell lines (data not shown)." (PMID 24489649, 2014).
neutropenia (18 papers, 1997 to 2026). A decrease in the number of neutrophils found in the blood. "Recombinant granulocyte colony-stimulating factor (r G-CSF) is most commonly used to treat neutropenia, and recombinant human erythropoietin is used to stimulate erythropoiesis." (PMID 34832856, 2021). "Since JAK2 is downstream of erythropoietin (EPO), granulocyte-macrophage colony-stimulating factor (GM-CSF), and thrombopoietin (TPO), neutropenia has been found in clinical trials with the JAK inhibitors baricitinib and tofacitinib both of which target JAK2 to some extent." (PMID 33343569, 2020).
pulmonary hypertension (18 papers, 2014 to 2026). Increased pressure within the pulmonary circulation due to lung or heart disorder. "Increased erythropoietin (EPO) in patients with familial/idiopathic erythrocytosis and pulmonary hypertension is associated with mutations in EGLN1 (PHD2) and EPAS1 (HIF2α); a drug inhibiting HIF2α activity is used for clear cell renal cell carcinoma (ccRCC) treatment." (PMID 37449559, 2023). "Therefore, decrease tissue oxygen delivery due to high Hgb F and increased erythropoietin were found to be associated independently with pulmonary hypertension (defined as TRV ≥ 2.5 m/s)." (PMID 37020484, 2023). "We have revealed a protective role of the endogenous erythropoietin (Epo)/Epo receptor (EpoR) system against the development of pulmonary hypertension (PH)." (PMID 30562953, 2018). "The stabilizing HIF-1α can also induce numerous physiological responses to compensate for the decreased tissue oxygen supply, including the production of erythropoietin (EPO), which can cause an increase in hemoglobin, may result in secondary erythrocytosis and pulmonary hypertension." (PMID 37887394, 2023). "EPO increases regardless of hypoxemia from a variety of causes, including COPD, pulmonary hypertension, interstitial lung disease, or heart failure." (PMID 33273655, 2020).
retinal degeneration (18 papers, 2009 to 2026). Degeneration of the retina. "Delivery of EPO-R76E vector can be used as a tool to prevent retinal degeneration induced by RPE oxidative stress, which is implicated as a potential cause of Age-Related Macular Degeneration." (PMID 34070383, 2021). "One group utilized a N-methyl-N-nitrosourea (NMU) induced model of retinal degeneration with rapid progression in a mouse model that was treated with an AAV2 vector encoding EPO (AAV-2/2-mCMV-EPO)." (PMID 33920974, 2021). "However, the potential of EPO to limit retinal degeneration associated with age-related macular degeneration (AMD) has not been explored." (PMID 34070383, 2021). "Erythropoietin (EPO), a hematopoietic cytokine with neuroprotective properties, has been shown to reduce apoptosis and retinal degeneration." (PMID 41294847, 2025). "Transgenic overexpression of the EPO gene alleviated photoreceptor apoptosis in a mouse model of light-damaged retina, which reduced the degree of retinal degeneration." (PMID 38638334, 2023). "For example, systemic administration of recombinant human erythropoietin (EPO) or an increased EPO level through hypoxia induction protected photoreceptor cells in a mouse model of light-induced retinal degeneration." (PMID 38638334, 2023). "A previous study found that overexpression of a modified form of EPO specifically in the RPE reduced retinal degeneration in response to oxidative stress." (PMID 35884958, 2022). "A modified form of EPO, EPO-R76E has attenuated erythropoietic activity but is effective in inhibiting apoptosis, oxidative stress, and inflammation in several models of retinal degeneration." (PMID 34070383, 2021). "EPO-R76E over-expression in RPE delayed the retinal degeneration as measured by light microscopy in RPE specific Sod2 knockout mice." (PMID 34070383, 2021). "Several pioneering experiments have demonstrated that the intraocular delivery of EPO can protect against retinal degeneration." (PMID 30744451, 2019). "Accumulating evidence makes EPO particularly attractive in preventing retinal degeneration in the early stages of retinal diseases." (PMID 28289375, 2017). "And subretinal transplantation of EPO gene-modified rat mesenchymal stem cells (rMSCs) worked better than rMSCs alone for sodium iodate (SI)-induced retinal degeneration in rats." (PMID 28289375, 2017). "Findings from a study demonstrated that subretinal injection of EPO AAVs resulted in approximately an 8 μm thicker outer nuclear layer (ONL) in retinas of retinal degeneration slow (rds) mice compared to the control group." (PMID 28289375, 2017). "Several gene engineering studies have demonstrated that MSC secreting erythropoietin (EPO) or brain-derived neurotrophic factor provided persistent neural protective effect in retina degeneration models." (PMID 26818606, 2015). "Taken together, the current study provides a rational strategy whereby MSCs could serve as a candidate for the delivery of EPO therapeutic gene in the treatment of retinal degenerations." (PMID 30108483, 2018). "Our results established a proof-of-concept that MSCs could be used as a candidate for the delivery of EPO therapeutic gene in the treatment of retinal degenerations." (PMID 30108483, 2018). "Therefore, early administration of EPO at a proper dose for retinal degeneration is important, for it can activate endogenous EPO-R in the affected tissue through stimulation of potent ischemic preconditioning." (PMID 28289375, 2017). "Treatment with EPO-R76E may widen the therapeutic window for retinal degeneration patients by increasing the number of viable cells." (PMID 27299810, 2016). "There is evidence that systemic EPO administration may protect retinal photoreceptors from light-induced apoptotic pathways in retinal degeneration models." (PMID 19930719, 2009). "Moreover, elevated EPO could achieve a relief effect on retinal degeneration in rds mice, another retinal degeneration mouse model." (PMID 38638334, 2023).
retinal degeneration (continued). "Subretinal transplantation of rat MSCs or engineered erythropoietin (EPO)-expression rat MSCs into a sodium iodate (SI)-induced rat model of retinal degeneration protected RPE and retinal neurons; EPO expression MSCs had an even greater effect." (PMID 33551729, 2020). "In this study, we used recombinant Adeno Associated Virus (AAV) to provide long-term sustained delivery of EPO-R76E and demonstrated its effects in a mouse model of dry-AMD in which retinal degeneration is induced by oxidative stress in the retinal pigment epithelial (RPE) cells." (PMID 34070383, 2021). "The application of EPO in treating retinal degeneration is not a new concept, as findings have indeed shown its efficacy in protecting the retina." (PMID 33987180, 2021). "However, a recent study by Meng and colleagues reported that EPO’s therapeutic effects occur independently of increased blood cell volume, a finding also supported in the context of retinal degeneration, in which tissue improvement was detected without a concomitant increase in haematocrit." (PMID 24344874, 2013). "Therefore, the subretinal delivery of EPO may not be effective for all retinal degeneration." (PMID 33920974, 2021).
sickle cell disease (18 papers, 2009 to 2026). Sickle cell anemias are chronic hemolytic diseases that may induce three types of acute accidents: severe anemia, severe bacterial infections, and ischemic vasoocclusive accidents (VOA) caused by sickle-shaped red blood cells obstructing small blood vessels and capillaries. "It is also suggested that children with sickle cell anaemia have greater tendency of having RV dysfunction because they have higher circulating erythropoietin concentrations." (PMID 32438903, 2020). "The authors confirmed by multiple linear regression that lower hemoglobin concentration was correlated with higher erythropoietin concentration and higher Hb F percentage among sickle cell disease patients." (PMID 24106994, 2013). "Erythropoietin can affect eNOS expression in different ways and eNOS expression is increased in animal models of sickle cell anemia." (PMID 22303468, 2012). "The role of erythropoietin (EPO) in sickle cell anaemia (SCA)." (PMID 38463100, 2024). "It’s important to note that while EPO therapy offers potential benefits, its effectiveness in improving outcomes in sickle cell disease may vary among individuals." (PMID 38463100, 2024). "EPO therapy might decrease the frequency of blood transfusions required by individuals with sickle cell disease." (PMID 38463100, 2024). "The role of erythropoietin, hypoxia, erythroid-dependent soluble factors and iron in regulating hepcidin transcription are discussed as well as differences and similarities in iron homeostasis between thalassemia syndromes and sickle cell disease." (PMID 21415988, 2009).